DMBT1 (deleted in malignant brain tumors 1)
Diseases named in the same sentence as DMBT1 in open-access papers (continued):
Sharing a sentence is not in itself a finding about the gene and the disease.
tumor (continued). "We selected DMBT1 (Deleted in Malignant Brain Tumors 1), a gene involved in innate immunity, cell differentiation and tumour suppression, to explore further the effects of PTEN genotype and SF on gene expression and splicing." (PMID 20626841, 2010). "It has been proposed that translocation of DMBT1 to the ECM triggers cellular differentiation, whereas a loss of expression of DMBT1 favours tumor cell growth." (PMID 15301691, 2004). "We studied the expression of DMBT1 (deleted in malignant brain tumor 1), a putative tumor suppressor gene, in normal, proliferative, and malignant breast epithelium and its possible relation to cell cycle." (PMID 15301691, 2004). "Recently, a second candidate tumour-suppressor gene, DMBT1, was identified in this chromosomal region." (PMID 9888459, 1999). "The effect of tumor-derived DMBT1 on cancer metastasis was then assessed DMBT1 overexpression and knockdown did not cause obvious changes in cancer cell growth, invasion or apoptosis." (PMID 40796724, 2025). "The mechanism of KC regulation by tumor-derived, extracellular DMBT1 was further analyzed." (PMID 40796724, 2025). "Meanwhile, DMBT1 knockdown in murine AT3 also inhibited tumor-induced CD62L+ polarization." (PMID 40796724, 2025). "Notably, REG3A has been identified as a positive regulator of DMBT1, potentially counteracting H. pylori-mediated silencing of this tumor suppressor." (PMID 40723277, 2025). "Additionally, the malignant brain tumours 1 protein gene (DMBT1) had an increased expression in the “18hr PB Only” treatment group compared to the “Larvae Only” control." (PMID 38650950, 2024). "Notably, DMBT1, known as a tumor suppressor in several cancers, exhibited the strongest negative fold change." (PMID 39252972, 2024). "The mutation frequencies of FAM83B, ZNF585A, DMBT1, ACACA, NOVA1, PCTH1, and ADAMTS7 were significantly higher in the high‐risk group, suggesting that these mutations may contribute to tumor development." (PMID 35616307, 2023). "DMBT1, as a tumor suppressor and archetypal link between inflammation and cancer, may provide essential clues about how innate immunity relates to regenerative processes in cancer." (PMID 35031021, 2022). "Finally, the correlation of deletion in DMBT1 expression with overall immune status, tumor purity, and human leukocyte antigen (HLA) gene expression profile was analyzed." (PMID 34422633, 2021). "The ssGSEA results demonstrated that tumor purity of the high expression of DMBT1 in TCGA was significantly higher than that of the low expression of DMBT1, which suggested that infiltrating stromal/immune cells existed in the TME of high-expression DMBT1 samples." (PMID 34422633, 2021). "In conclusion, Reg3A may act as a novel tumor suppressor by promoting DMBT1 expression, which may be a potential therapeutic target in patients with GC." (PMID 34605357, 2021). "Considering the clues above, we hypothesized that Reg3A acts as a tumor suppressor by targeting DMBT1 in GC." (PMID 34605357, 2021). "Specifically, these mutations are located on five tumor suppressors (SDHA, RB1CC1, PTCH1, DMBT1, BCR) and eight proto-oncogenes (MERTK, CSF1R, MYB, ROS1, PCM1, FGFR2, MYH11, BRCC3) and have an allele frequency lower than 0.01 in the Genome Aggregation Database (GnomAD)." (PMID 33466296, 2021). "DMBT1 encoding protein belongs to the scavenger receptor cysteine rich (SRCR) super family involved in mucosal immune defense, epithelial differentiation and tumor suppression." (PMID 32607130, 2020). "Finally, DMBT1 is a secreted scavenger receptor, which is a potential tumour suppressor and reportedly increases sensitivity to the chemotherapeutic cisplatin." (PMID 32734521, 2020). "Thus, consistent with tumor suppressor function, decreased expression of DMBT1 mRNA occurs frequently in GBC." (PMID 27637083, 2016).
tumor (continued). "Furthermore, binding of deleted in malignant brain tumors 1 (DMBT1), a tumor-suppressor gene, with lncRNA colorectal neoplasia differentially expressed (CRNDE), and cellular inhibitor of apoptosis protein 1 (c-IAP1) was found to promote PI3K-AKT signaling pathway in GBC." (PMID 34944491, 2021). "The change in expression of salivary DMBT1 with accompanying changes in the microbiome suggests the possibility that DMBT1 may be important in modulating the oral microbiome and/or the tumor microenvironment to maintain homeostasis and resist carcinogenesis and tumor progression." (PMID 38037123, 2023). "DMBT1 was a member of the SRCR superfamily and also a tumor suppressor, playing a role in innate immune defense and inflammation." (PMID 36452144, 2022). "Consistent with the results obtained with bioinformatics, it was revealed that CA12 and AHNAK2 mRNA levels were significantly upregulated in tumor tissues compared to adjacent tissues, whereas MMAA and DMBT1 mRNA levels were downregulated analogously." (PMID 35847888, 2022). "Therefore, the DMBT1 gene may be able to inhibit the progression of the tumor." (PMID 34422633, 2021). "Most interesting were the 4 genes that function as tumor suppressors: C10orf90, RARRES1, DMBT1, and SCGB3A1." (PMID 34769520, 2021). "Deleted in malignant brain tumors 1 (DMBT1) is deleted during cancer progression and as a potential tumor-suppressor gene in various types of cancer." (PMID 27637083, 2016). "Two putative tumour suppressor genes, namely PTEN/MMAC1 and DMBT1, have been identified on chromosome 10q23.3 and 10q25, respectively." (PMID 12107846, 2002). "Reciprocally, DMBT1 knockdown in LvM16 impaired the capacity of LvM16 CM to induce CD62L+ polarization and Ccl8 expression of primary KCs, leading to suppressed NET formation in vitro when neutrophils were co-cultured with tumor-pretreated KCs." (PMID 40796724, 2025). "Further modifications led to the creation of D4RA6H, designed from the DMBT1 sequence (GRVEVLXXXXW), with the “XXXX” motif replaced by an arginine-rich sequence (RRRR) for siRNA binding, and fused with a CD44-targeting moiety (KPSSPPEEHH) to increase tumour cell selectivity." (PMID 41129852, 2025). "The PCR and Western blot analysis results suggested that CA12 and AHNAK2 were significantly upregulated, while MMAA and DMBT1 were downregulated in the tumor sample compared with adjacent tissues, and in non-recurrent samples compared with non-recurrent samples in COAD." (PMID 35847888, 2022).
cancer (33 papers, 2004 to 2025). A tumor composed of atypical neoplastic, often pleomorphic cells that invade other tissues. "This study suggests for the first time a potential role for gp-340/DMBT1 polymorphisms in human diseases beyond cancer, as it implies the gp-340 I protein as a caries susceptibility protein." (PMID 17562017, 2007). "The loss of DMBT1 expression appears to take place early, i.e. already at the time of transition from hyperplastic lesions to carcinoma, as it has been reported in oesophageal squamous cell carcinomas." (PMID 15301691, 2004). "Mutations of PIK3C2G, PRKDC and DMBT1 are also commonly found in cancer patients." (PMID 36038950, 2022). "This resembles the DMBT1 expression patterns observed in the human respiratory tract and in associated inflammation and carcinomas and suggest that the variable DMBT1 expression in the normal mammary gland epithelium may result from the necessity of DMBT1 induction." (PMID 15301691, 2004). "The effect of DMBT1 was dependent on KCs, as Clod treatment to deplete KCs in the liver effectively suppressed NET formation and liver metastasis of DMBT1-overexpressing cancer cells." (PMID 40796724, 2025). "Several previous studies elucidated that DMBT1 was obviously expressed in normal tissues compared with cancer or disease tissues." (PMID 34422633, 2021). "Up to published results, the selected genes were either playing a role in cancer development as Dmbt1, considered candidate tumor suppressor genes for several cancer types, or suppressors of mRNA translation and protecting from cancer development as Cpeb2." (PMID 30621213, 2019). "Sustained elevation of mucins, glycoproteins closely related to DMBT1, has been shown to promote the transition from chronic inflammation to cancer." (PMID 28423364, 2017). "Several studies showed Deleted in malignant brain tumors 1 (DMBT1) have functions in many kinds of cancer." (PMID 27637083, 2016). "DMBT1 protein expression was down-regulated in the cancerous lesions compared to the normal and/or hyperplastic epithelium adjacent to carcinomas (3/55 positive carcinomas versus 33/42 positive normal/hyperplastic epithelia; p = 0.0001)." (PMID 15301691, 2004). "Deleted in malignant brain tumors 1 (DMBT1), which is highly secreted in saliva, is one such protein with a significant function in epithelial equilibrium, inflammation, innate immunity, and more recently, in the cancer microenvironment." (PMID 38037123, 2023). "Among the genes showing the strongest upregulations in M. refringens‐infected individuals (log2 fold >4), several genes are known to be involved in immune response processes or cancer‐like pathologies (prominin, DMBT1, 2‐proprotein convertase subtilisin/kexin), cell adhesion (contactin, laminin)." (PMID 36426129, 2022). "In addition, DMBT1 is significantly downregulated in a number of cancers affecting multiple organs including brain, lungs, pancreas, oral cavity, prostate, cervix, and skin." (PMID 25873979, 2015). "Mindful of these limitations, future studies could be focused, for example, to analyze if YB could stimulate DMBT1 in cancer patients and if YB could facilitate the availability of DMBT1 in tumor sites where DMBT1 is downregulated." (PMID 25873979, 2015). "Sections from 17 benign lesions and 55 carcinomas were immunostained with anti DMBT1 antibody (DMBTh12) and sections from 36 samples, were double-stained also with anti MCM5, one of the 6 pre-replicative complex proteins with cell proliferation-licensing functions." (PMID 15301691, 2004). "Surprisingly, homologous structures, namely the CUB and SUSHI domains, are shared between CSMD1 and other proteins that play important roles in cancer progression, such as SEZ6L and DMBT1." (PMID 27756250, 2016). "All the down-regulated genes, in this Panel 3 showed their significant up-regulation in most of many types of cancers (TGM2, CSNK1A1, CTNNA1, NAMPT/Visfatin, TNFRSF1A, ETS1, SRC-1, FN1, APLP2, DMBT1/SAG, AIB1, AZIN1)." (PMID 23122428, 2012).
cancer (continued). "Like DMBT1, spatial proteomics implicates MARCKS as being involved in the transition toward cancer." (PMID 39252972, 2024). "However, lack of DMBT1 expression in non-neoplastic biliary tissue of CCA patients was associated with poor survival while no significant impact on outcome was observed when DMBT1 expression was reduced in cancer cells." (PMID 39034327, 2024).
infection (21 papers, 2010 to 2024). The state of being infected such as from the introduction of a foreign agent such as serum, vaccine, antigenic substance or organism. "The reduced number of neutrophils following infection with ΔespO was consistent with lower abundance of Mmp9 and was mirrored by a global decrease in expression of genes encoding AMPs, with the exception of Dmbt1 and Iod1." (PMID 30365535, 2018). "Understanding the consequences of variation of this molecule in the mucosal innate immune response to infection will be an important aspect of understanding the role of DMBT1 in health and disease." (PMID 35494225, 2022). "The protective mechanism of DMBT1 in our in vitro and in vivo infection models is likely to involve suppression of twitching motility, given that twitching is critical to pathogenesis in the cornea." (PMID 28489917, 2017). "One study used human aortic endothelial cells (HAECs) to model S. mutans interactions during IE, and while they did not directly investigate the role of AgI/II proteins, they instead looked at expression of known AgI/II protein receptor DMBT1 (SAG/gp340) in response to infection." (PMID 33329493, 2020). "DMBT1 expression is upregulated following infection and/or inflammation." (PMID 28423364, 2017). "Thus, discovery that DMBT1 modulates bacterial virulence factor expression adds to our understanding of how mucosal fluids defend tissue surfaces against infection." (PMID 28489917, 2017). "We therefore hypothesized that breast milk may contain DMBT1 and that DMBT1 levels in breast milk could potentially correlate with infections in the neonates." (PMID 23034003, 2012). "Additionally, expression of mouse DMBT1 in the gastrointestinal tract is regulated by bacteria, and its expression is increased during infection." (PMID 20573196, 2010). "Therefore, taken together, these data suggest that DMBT1 may modulate gastric epithelial damage induced by infection and the inflammatory process and that its deletion promotes disease progression during H. pylori infection." (PMID 28423364, 2017). "Downregulation of Dmbt1 in SCTLD-infected corals may therefore render corals unable to maintain mucosal microbial homeostasis, leading to a loss of the protective capabilities of their surface mucus layer and making them susceptible to secondary infection by opportunistic bacteria." (PMID 37217477, 2023). "Infection of WT mice with H. pylori resulted in increased Dmbt1 mRNA expression; however, H. pylori load was not different between Dmbt1−/− and WT." (PMID 28423364, 2017).
bacterial infection (2 papers, 2023 to 2024). "SLPI, coexpressed with DMBT1 (coexpression score 0.078 from the GEO database, STRING), modulates inflammatory responses after bacterial infection, while OLFMA4 and SCGB1A1 are also associated with salivary gland function." (PMID 39580055, 2024).
respiratory disease (2 papers, 2015 to 2022). "Because understanding VEGF regulation is thus critical for understanding the basis of respiratory disease, we here addressed possible links between the secreted factor DMBT1 and VEGF." (PMID 25885541, 2015).
DMBT1 also shares sentences with these, for which no sentence is quoted: dental caries (4 papers); colon carcinoma (3); cystic fibrosis (2); HIV-1 infection (2); lymphoma (2); thyroid cancer (2); ulcerative colitis (2); adenocarcinoma (1); amyloidosis (1); atrophic gastritis (1); autoimmune disease (1); bacterial endocarditis (1); bacterial pneumonia (1); breast tumors (1); Chronic Fatigue Syndrome (1); chronic sinusitis (1); colorectal adenoma (1); colorectal tumors (1); conjunctivitis (1); dry eye syndrome (1); ductal carcinoma in situ (1); ductus arteriosus (1); duodenal cancer (1); gastric adenocarcinoma (1); gastrointestinal disease (1); gastrointestinal tumors (1); hematological disease (1); invasive carcinoma (1); Jaundice (1); lung squamous cell carcinoma (1).
A further 19 diseases each share a sentence with DMBT1 in 1 paper.